DNMT3A (DNA methyltransferase 3 alpha)
Diseases named in the same sentence as DNMT3A in open-access papers (continued):
Sharing a sentence is not in itself a finding about the gene and the disease.
tumor (continued). "To investigate whether TET2/DNMT3A mutations were detectable in human tumor samples, we analyzed frequency of TET2 and DNMT3A mutations in a spectrum of over 100 cancer types." (PMID 34039392, 2021). "Mechanistically, DDX3X represses the expression of stemness genes via upregulation of the expression of a subset of tumour-suppressive miRNAs, including miR-200b, miR-200c, miR-122 and miR-145, by reducing DNMT3A (DNA methyltransferase 3A) binding and hypermethylation on their promoter regions." (PMID 33627125, 2021). "Interestingly, similar findings were reported by others, who associated the aberrant DNA methylation found in UL with an increased DNMT1 and DNMT3a mRNA expression in tumor samples compared to myometrium." (PMID 34233687, 2021). "miRNAs may also play a significant role in the DNA methylation pattern, as, for example, miR-29 inhibits DNMT3a and DNMT3b enzymes in several tumor types." (PMID 33878138, 2021). "However, DNMT3a overexpression substantially increased the tumor volumes and weight after 30 days growth." (PMID 33589600, 2021). "The drug sensitivity of A549-BMP cells to Doxorubicin hydrochloride (DOX) was increased; the growth and migration capability of A549-BMP cells were inhibited along with the decreased protein level of Bcl-2 and DNMT3a; the growth of tumor in nude mice injected with A549-BMP cells were inhibited, too." (PMID 31901898, 2020). "Up regulation of miR-143 was found in BE and EAC, suggesting miR-143 may play an important role in dysplaysia and tumor develoment, possibly through targeting DNMT3A." (PMID 32903213, 2020). "However, DNMT3A was found to methylate and inactivate the HIF-2α gene EPAS1, and inactivation of DNMT3A in the early stages of tumor cell progression leads to abnormal activation of EPAS1." (PMID 33109235, 2020). "Moreover, in previous studies, the protein expression of both DNMT3a and DNMT3b was found to be increased in tumor cell lines." (PMID 32908633, 2020). "In addition to DNMT3A, mutations in genes such as JAK2 and TET2, which are also located in hematopoietic clones, can confound the detection of tumor‐derived variants in blood." (PMID 30672098, 2019). "The most likely explanation for this discrepancy is that DNMT3A mutations detected in ctDNA are involved in hematopoietic clones with undefined clinical implications, rather than tumor‐derived." (PMID 30672098, 2019). "Primary AML tumor samples were selected based on having known HLA haplotypes for HLA-A, B, C and HLA-DR, and at least one or more common recurrent mutations in either NPM1, FLT3, DNMT3A, IDH1, IDH2, KIT, or RAS from previous clinical evaluation." (PMID 31291378, 2019). "Taken together, MICMIC along with MRA was able to identify causal events in tumorigenesis involving DNA methylation of distal regulatory regions, which we were able to verify via epigenetic editing by dCas9 fused with TET1 or DNMT3A-3 L and identify novel oncogenes/tumor-suppressors in the process." (PMID 29871649, 2018). "DNMT3A was also significantly down-regulated by over 1.5-fold in the GBM50 tumours." (PMID 30208958, 2018). "Although the function of DNMT3A as a whole has been described in tumour progression, its isoforms exhibit different sub-nuclear localisation and expression patterns, suggesting that each DNMT3A isoform may have unique functional specificity." (PMID 29717263, 2018). "In addition, Dnmt3a acts as a potent tumor suppressor in lung tumorigenesis, to promote adenoma progression but not initiation, downstream of oncogenic K-Ras." (PMID 28425913, 2017). "Moreover, transcriptional inactivation of SALL3 was associated with aberrant methylation of other tumor-related genes and TET1, TET2, and DNMT3A levels in HNSCC." (PMID 28616099, 2017).
tumor (continued). "To further dissect the early molecular changes that might result in the tumor-suppressing role of Dnmt3a in the epidermis, we did a short (6-week long) DMBA/TPA carcinogenesis treatment." (PMID 28425913, 2017). "DNMT3A knockdown prevented VEGFA‐driven miR‐128‐2 loss, and the increase in Bmi1 and tumor spheres." (PMID 28179359, 2017). "In addition, we identified that SATB2 can bind to DNMT3A and upregulate its protein expression, thereby indirectly affecting tumor growth and miR-449a and miR-34a expression via DNA methylation." (PMID 29254139, 2017). "Hence, these results suggest that most of the transcriptome changes observed in tumors upon deletion of Dnmt3a occur early, and that the transition from the pre-cancerous epithelium to tumor growth occurs subsequently by bypassing apoptosis." (PMID 28425913, 2017). "SATB2 inhibited tumor growth indirectly via DNMT3A and miR-449a/34a expression." (PMID 29254139, 2017). "We next tested whether the increase in the expression of genes involved in lipid metabolism was required for the earlier onset of tumorigenesis and increased tumor burden in Dnmt3a-cKO mice." (PMID 28425913, 2017). "Due to the lower frequency of PTCL development in Dnmt3a-deficient mice, larger cohorts of mice will need to be analyzed to determine whether Dnmt3a tumor suppressor function in prevention of PTCL is also autonomous to hematopoietic system." (PMID 27677595, 2016). "To investigate if the increased level of DNMT3A proteins in the shUHRF2-expressing A549 cells is responsible for reduced tumor growth, we established A549 cell lines that stably expressed either the wild-type DNMT3A or its R882C mutant, which has an impaired enzymatic activity." (PMID 27462454, 2016). "Through this molecular mechanism, reduction of DDX3 sustains DNMT3A protein stability and facilitates epigenetic silence of tumor-suppressive miRNA transcriptions to promote CSC phenotypes as well as tumorigenesis, which reinforces the tumor suppressor role of DDX3 in HCC." (PMID 27344963, 2016). "Indeed, HIF-1alpha-transactivated DNMT3a methylates DNA, which inhibits tumor suppressors and leads to tumor growth." (PMID 26955619, 2016). "We observed that MTHFR and DNMT3A promoters show different methylation levels between blood and tumor tissue; this data was observed in the total population composed of 69 patients as well as in the smaller subgroup of 44 patients for whom healthy thymic specimens were available." (PMID 27999265, 2016). "Deletion of DNMT3A promotes tumor progression and enables cells to invade into bronchiole." (PMID 27724883, 2016). "In further support of this conclusion, we demonstrated that overexpression of wild type but not enzymatic activity-deficient DNMT3A mutant phenocopied the impaired tumor growth result observed for UHRF2 knockdown A549 cells." (PMID 27462454, 2016). "However, in our data, even though DNMT3A expression was highly upregulated, total methylation levels were down-regulated in the tumor samples although a slight positive correlation was observed between global methylation level and expression of each DNMT." (PMID 27137948, 2016). "Regarding the DNMTs, the writers of DNA methylation reactions, in this study only DNMT3A showed increased methylation levels in tumor tissue, comparable to those found in adjacent thymic tissue, with respect to blood; the other two DNMTs genes, DNMT1 and DNMT3B, resulted hypomethylated." (PMID 27999265, 2016). "Collectively, these results demonstrate that DNMT3A promotes tumor cell proliferation in vitro and in vivo and therefore may contribute to maintaining malignant phenotype in GC." (PMID 26350239, 2015).
tumor (continued). "Although the expression of p18INK4C was partially affected by DNMT1, no significant upregulation of DNMT1 (P > 0.05) or DNMT3B (P > 0.05) mRNA levels was observed in 35 GC tissues (the same tissues used to detect DNMT3A expression) compared with non-tumor tissues." (PMID 26350239, 2015). "Conceivably, as well as contributing to a programmed pro-differentiation/anti-self-renewal tumor suppressor function, DNMT3a might also promote chromostasis to restrict more stochastic epigenetic variation and plasticity in HSCs." (PMID 26046760, 2015). "All of these results indicate that DNMT3A facilitates tumor development." (PMID 26350239, 2015). "DNMT3a overexpression after treatment with tumor DNA infers a potential connection between the methylation status of tumor tissue derived DNA and the mechanism of action of tumor tissue derived DNA sequences acting through DNA sensing receptors." (PMID 26133168, 2015). "Depending on the cell type or individual tumour type, the specific DNMT member implicated in this mechanism may be different; however, in the NMuMG model where EMT is potently elicited, DNMT3A is the most likely candidate." (PMID 25492890, 2015). "Re-expression of factors targeting DNMT3a expression significantly decreased tumor growth." (PMID 26133168, 2015). "We found higher DNMT1 mRNA levels compared to de novo DNMT in both tissues and in all experimental groups, according to the literature, and a coordinated expression of DNMT1, DNMT3a and DNMT3b in mammary gland and tumor, as it has been described in several tissues." (PMID 26401660, 2015). "Downstream epigenetic regulators of OCT4, such as DNMT3a/b, could be involved in this concerted silencing of tumor suppressor genes." (PMID 21952072, 2011). "Importantly, miR-29 family members were also reported to have an important role in preventing epigenetic silencing of tumour suppressors due to de novo methylation in cancer, as they directly suppress DNMT3A and B." (PMID 20628397, 2010). "On the other hand, the reactivation of tumour suppressor genes by demethylation could represent another mechanism through which miR-143 exerts its tumour suppressor function by repressing DNMT3A." (PMID 19638978, 2009). "Consistent with previous studies, TET2 and DNMT3A mutations were observed in non‐tumor cells including myeloid or B‐cells, suggesting early founding mutation in a progenitor cell in a subset of cases, but other mutations like IDH2, RHOA, and CD28 appeared to be tumor‐specific." (PMID 40510016, 2025). "Therefore, we speculated whether Diazinon could up-regulate the expression of TAT in BC and play a tumor suppressor role by inhibiting DNMT3A/3B." (PMID 39334853, 2024). "Hence, PUMA upregulation mediated by iodine-fortified lettuce could be the trigger for the epigenetic activation of tumor suppressor genes through the MDM2/RB/DNMT3A pathway." (PMID 37373017, 2023). "Furthermore, DNMT3A knockout CAR-T cell therapy effectively raised anti-tumor responses." (PMID 37398660, 2023). "Thus, DNMT3A represents one of the most important tumor suppressor genes in hematological malignancies, highlighting the need to improve our understanding of its basic biological function(s) and develop new strategies for targeting it, especially in the context of DNMT3A mutations." (PMID 36163326, 2022). "In addition, we found that AMG 706 treatment reduced tumor cell proliferation and migration abilities could be reversed by MrgprF knockdown, possibly via reducing DNMT3A and DNMT3B expression." (PMID 35504869, 2022). "In addition, our results indicated that decreased Dnmt1 and Dnmt3a expression abrogates promoter CpG methylation and depresses inflammatory Casp1 and Casp11 as well as pyroptotic executor Gsdmd to transcriptionally prime Mll4−/− tumor cells for pyroptosis." (PMID 36323669, 2022). "Additionally, Dnmt3a-KO T cells resulted in superior graft-versus-tumor activity." (PMID 35608905, 2022).
tumor (continued). "Additionally, it has been demonstrated that the active features of BC-associated fibroblasts cells, major components of the tumor microenvironment, could be normalized through drug targeting of DNMT1/DNMT3A and the consequent modulation in gene methylation." (PMID 36091786, 2022). "In addition to STAT3, these included SMARCA2, a tumor suppressor involved in various cancers, SOCS1, a STAT-inhibitor, DNMT3A, with known somatic mutations in the context of clonal hematopoiesis and PPP3CA encoding calcineurin-A, involved in T-cell receptor signaling." (PMID 34874980, 2021). "In addition, our results also suggested that Sohlh2 might upregulate Klotho’s expression level by downregulating the expression of DNMT3a and thus functioned as a tumor suppressor in human RCC." (PMID 35127476, 2021). "Besides, both univariate and multivariate Cox analyses revealed that the risk score could act as an independent prognostic factor in HNSCC, implying that NSUN5, DNMT1, and DNMT3A could be involved in tumor oncogenes and suppressors." (PMID 33912441, 2021). "The results showed that the expression of TYMS was negatively correlated with tumor mutational burden and microsatellite instability, and positively correlated with the expression of four methyltransferases (DNMT1: red, DNMT2: blue, Dnmt3A: green and DNMT3B: purple)." (PMID 35003215, 2021). "However, G9a and GLP induce the formation of the DNMT3a-MPP8-GLP/G9a silencing complex through DNMT3a-K44me2 (mouse; K47me2, human) methylation and therefore may facilitate the tumor-suppressive role of DNMT3a." (PMID 33088284, 2020). "Moreover, they showed that Dnmt3b loss does not accelerate tumor initiation, but synergistically cooperates with DNMT3A loss during development toward more aggressive and metastatic stages of the malignancy." (PMID 34968242, 2020). "Among ERGs that could be classified as tumor suppressors, KMT2D, KMT2C, ARID1A, ATRX, CREBBP, and PBRM1 were frequently mutated in many cancer types, whereas oncogenic ERGs were each mutated in specific cancer types, mainly IDH1 in LGG and DNMT3A in LAML." (PMID 32963031, 2020). "Furthermore, transcriptional inactivation of Sal-like protein 3 (SALL3) was found to be associated with aberrant methylation of other tumor-related genes and ten-eleven translocation (TET) family genes, as well as DNA methyltransferase 3 alpha (DNMT3A) levels, in HNSCC." (PMID 30901947, 2019). "Finally, it is worth noting that DNMT3A and TET2 mutations are also frequently observed in age-related clonal hematopoiesis, suggesting a central role of these two enzymes in age-related phenotypes and tumor development." (PMID 29069286, 2018). "However, loss of Dnmt3a-but not Dnmt3b-increases the number of carcinogen-induced squamous tumors, without affecting tumor progression." (PMID 28425913, 2017). "However, Dnmt3a has a critical role in suppressing carcinogen-induced squamous tumor initiation, but not progression, while both Dnmt3a and Dnmt3b concertedly prevent tumor progression." (PMID 28425913, 2017). "Immunohistochemistry staining for DNMT3A confirmed increased levels of DNMT3A in the tumors derived from the shUHRF2-expressing A549 cells, indicating that increased DNMT3A levels upon downregulation of UHRF2 are associated with drastically reduced tumor growth." (PMID 27462454, 2016). "Therefore, DNMT3A variation may enhance tumor cell invasiveness through altering migrating mechanisms." (PMID 27724883, 2016). "Expression overlays of six RNA modification genes selected by the LASSO Cox model (DNMT1, DNMT3A, HNRNPC, IGF2BP2, NSUN5, and ZC3H13) demonstrated variable distribution across the tumor microenvironment." (PMID 40565233, 2025). "In AT/RT, DNA hypermethylation is frequently observed partially due to DNMT1 and DNMT3A upregulation, and DNMT inhibitors impaired tumor growth in vitro and in vivo." (PMID 40599851, 2025).
tumor (continued). "The results showed that F. nucleatum and its culture supernatant did not increase the activity of DNMT1 and DNMT3B in COLO 205 cells or the activity of DNMT1, DNMT3A, and DNMT3B in subcutaneous tumor tissue of nude mice infected with F. nucleatum." (PMID 40458404, 2025). "Upregulated expression of DNMT3a was positively correlated with maximal tumour size, high T stage, lymphatic invasion, high AJCC 8th edition stage, and poor tumour differentiation." (PMID 39990668, 2025). "This progressive increase parallels the accumulation of methylated tumor-suppressor genes observed from normal liver tissue to HCC, situating DNMT3A within a broader tumorigenic methylation program." (PMID 41465346, 2025). "The observed divergence in the prognostic impact of DNMT3A and GMPS between PDAC and HCC underscores the importance of tumor-specific immune and metabolic contexts in shaping clinical outcomes." (PMID 41465346, 2025). "Knockdown of DNMT3A reduces proliferation, suppresses colony formation, and demethylates the PTEN promoter, implicating direct silencing of tumor suppressors." (PMID 41465346, 2025). "When the tumor microenvironment (TME) signatures were compared, it was evidenced that the effects of DNMT3A and GMPS are similar between HCC and PDAC." (PMID 41465346, 2025). "Tumor cells can upregulate DNMT3A or lose TET2 function, substituting DNA methylation for H3K27me3 marks to re-silence critical tumor suppressor genes and restore a malignant phenotype." (PMID 40032852, 2025). "Regarding DNMT3A and DNMT3B, they appear to play a protective role in the epidermis against tumour formation." (PMID 39846570, 2025). "To assess the DNMT3A and TET2 protein expressions in OSCC, we performed western blotting of six pairs of primary tumor and surrounding healthy tissue samples." (PMID 38246976, 2024). "Consistent with the finding that DNMT3A induces an aggressive phenotype of GBC in vitro, the in vivo tumor xenograft assay indicated that silencing DNMT3A inhibited GBC cell metastasis to the liver." (PMID 38380551, 2024). "The methylation degrees of DNMT3A and TET2 were statistically analyzed in correlation with clinical and pathological features (gender, age, lesion site, tumor size, clinical stage, pathological stage, and lymphatic metastasis)." (PMID 38246976, 2024). "In general, we identified Diazinon as a small molecule inhibitor targeting DNMT3A/3B, which up-regulates TAT expression, blocks the cell cycle in BC cells, and exerts tumor suppressor function." (PMID 39334853, 2024). "Taken together, we revealed that TAT is silenced by DNMT3A/3B in BC, especially in TNBC, which promotes the proliferation of tumor cells by supporting DNA replication, activating cell cycle, and enhancing DNA damage repair." (PMID 39334853, 2024). "Conversely, when DNMT3L expression is abnormal, DNMT3A can facilitate the methylation of CDO1 promoter, thus downregulating CDO1 expression and promoting tumor growth and metastasis." (PMID 38308276, 2024). "The expression of DNMT3A increased significantly when EZH2 was knocked down; CCL22 and CCR4 were downregulated in tumor tissues, and EMT-related protein expression also changed consistent with in vitro results." (PMID 39513112, 2024). "In summary, this study identified a novel mechanism by which LDHB suppressed HCC progression via DNMT3A-induced hypermethylation of LDHB promoter and remodeling tumor immune environment." (PMID 38739169, 2024). "Methylation β values of DNMT3A and TET2 were significantly correlated with gender, tumor size, extent of invasion, and clinical stage (P < 0.05)." (PMID 38246976, 2024). "The expression levels of three writers (DNMT1, DNMT3A, DNMT3B), two erasers (TET1, TET3), and eight readers (MBD4, ZBTB33, UHRF1, UHRF2, UNG, TDG, NTHL1, SMUG1) were dramatically higher in tumor tissues (p < 0.05)." (PMID 38317133, 2024). "Another study has recently shown that deletion of DNMT3A in human CAR T cells prevents exhaustion and enhances anti-tumor activity." (PMID 37452103, 2023).